CD58 (CD58 molecule)
Diseases named in the same sentence as CD58 in open-access papers (continued):
Sharing a sentence is not in itself a finding about the gene and the disease.
neuroblastoma (2 papers, 1993 to 2021). Neuroblastoma (NB) is the most common solid, extracranial childhood tumor. "In neuroblastoma, CD58 is critical for the susceptibility of it to the cytotoxic effects of LAK and NK cells." (PMID 34168659, 2021). "We find that LFA-3 (CD58), the ligand for CD2 is of predominant importance in predicting susceptibility of neuroblastoma to the cytotoxic actions of NK and LAK cells, while expression of ICAM-1 (CD54) may also modify susceptibility." (PMID 8494726, 1993). "Blocking CD58 on neuroblastoma cells could attenuate NK and LAK cytotoxicity." (PMID 34168659, 2021).
neuromyelitis optica (2 papers, 2014 to 2021). A rare inflammatory disease of the central nervous system characterized mainly by attacks of uni- or bilateral optic neuritis (ON) and acute myelitis. "It has reported that CD58 single-nucleotide polymorphisms (SNP), including 6 variations, rs12044852A/C (SNP1), rs2300747A/G (SNP2), rs1335532C/T (SNP3), rs1016140G/T (SNP4), rs1414275C/T (SNP5) and rs11588376C/T (SNP6), related to the risk of neuromyelitis optica (NMO)." (PMID 34168659, 2021).
pancreatic ductal adenocarcinoma (2 papers, 2021 to 2022). An infiltrating adenocarcinoma that arises from the epithelial cells of the pancreas. "Interestingly, in patients with pancreatic ductal adenocarcinoma, CD58 was upregulated in cancer tissues and associated with worse overall survival and disease-free survival." (PMID 36611312, 2022). "CD58 has been demonstrated to be abnormally expressed in multiple hematopoietic malignancies and solid tumors and plays an essential role in tumorigenesis and progression; however, its clinical significance and prognostic value in pancreatic ductal adenocarcinoma (PDAC) remain unknown." (PMID 34193136, 2021).
pheochromocytoma (2 papers, 2021 to 2025). "Similarly, CD58 correlated with MSI in breast invasive carcinoma (BRCA), CESC, KICH, LUAD, ovarian serous cystadenocarcinoma (OV), pheochromocytoma and paraganglioma (PCPG), THCA, and UCEC." (PMID 41438981, 2025). "The only pheochromocytoma analyzed (n = 1) showed a distinct CD56++ CD57+ GD2++ CD271+ CD9+ CD81+ CD90het CD58+ phenotype, in the absence of expression of CD10, CD99, CD117, EpCAM, nuMyoD1, and numyogenin." (PMID 34638431, 2021).
T cell lymphomas (2 papers, 2020 to 2023). "Defects in CD58 (either loss of expression or mutations) have been reported in B cell and T cell lymphomas (63, –65), and CD2 expression on tumor-infiltrating T cells has been shown to correlate with their function in several cancers." (PMID 36598945, 2023).
viral infection (2 papers, 2005 to 2025). "Mestas and Hughes (2004) highlighted that human immune systems contain unique immune cell subsets not found in mice (CXCR1, CD58 (LFA-3), CD40 on ECs, etc.), which can affect the study of viral infections and the immune response to AAV vectors." (PMID 39859531, 2025).
acute lymphoblastic leukemia (1 paper, 2025). Leukemia with an acute onset, characterized by the presence of lymphoblasts in the bone marrow and the peripheral blood. "In this study, we investigated the potential roles of ADAM10 and CD58 proteins in acute lymphoblastic leukemia (ALL) and chronic lymphocytic leukemia (CLL), both in their treated and untreated states, by comparing their expression levels to a healthy control group." (PMID 40746920, 2025).
adrenocortical carcinoma (1 paper, 2025). "CD58 expression showed significant associations with TMB in adrenocortical carcinoma (ACC), CESC, CHOL, LUAD, prostate adenocarcinoma (PRAD), skin cutaneous melanoma (SKCM), THCA, and uterine corpus endometrial carcinoma (UCEC)." (PMID 41438981, 2025).
asthma (1 paper, 2020). "CD58 is highly expressed on the eosinophils of asthmatic patients and increased expression of FcεRI on CD2high monocytes from asthma patients correlates with higher serum IgE levels." (PMID 32477356, 2020). "Surface expression of CD2 and its ligand, CD58, is increased on the monocytes and eosinophils of asthma patients, which correlate with elevated serum IgE levels, suggesting that CD2 may contribute to allergic airway inflammation." (PMID 32477356, 2020). "CD2 gene transcripts were also significantly elevated in the lungs of these asthma patients, consistent with prior reports demonstrating that CD2 and its ligand CD58 is increased on monocytes and eosinophils of asthma patients." (PMID 32477356, 2020).
atopic eczema (1 paper, 2025). A common chronic pruritic inflammatory skin disease with a strong genetic component. "For example, in a clinical pilot study, treatment with alefacept (a CD58-IgG1 fragment crystallizable (Fc) domain fusion protein) was found to reduce skin inflammation in cases of atopic eczema." (PMID 40612147, 2025).
B-cell acute lymphoblastic leukaemia (1 paper, 2022). "Specifically, although the BC ClearLLab 10C can easily discern normal B-cell precursors or haematogones from similar immunophenotypes present in minimal residual B-cell acute lymphoblastic leukaemia (B-ALL) disease, the CD58 marker is not included." (PMID 36483322, 2022).
B-cell acute lymphoblastic leukemia (1 paper, 2025). A neoplasm of lymphoblasts committed to the B-cell lineage, typically composed of small to medium-sized blast cells. "Using flow cytometry, we evaluated the impact of CD58 mean fluorescence intensity (MFI) on the probability of achieving measurable residual disease (MRD) negativity in patients with B‐cell acute lymphoblastic leukemia treated with inotuzumab ozogamicin (InO)." (PMID 39866945, 2025).
chondrosarcoma (1 paper, 2021). A malignant cartilaginous matrix-producing mesenchymal neoplasm arising from the bone and soft tissue. "In turn, tumor cells from the only chondrosarcoma (CDS) analyzed were also positive for GD2 and CD9, in addition to CD81 and CD90, and they lacked CD10, CD58, nuMyoD1, numyogenin, CD57, and CD99 expression." (PMID 34638431, 2021).
chronic inflammatory demyelinating polyneuropathy (1 paper, 2022). "Interestingly, a study comparing nerve biopsies of healthy patients and patients with chronic inflammatory demyelinating polyneuropathy (CIDP) identified that CD58 expressing SCs were only found in the latter." (PMID 36054432, 2022).
Chronic Myeloid Leukemia (1 paper, 2025). "Defective CD58 expression in Chronic Myeloid Leukemia (CML) progenitors impedes the normal proliferative response of T lymphocytes, resulting in abnormal adherence and clonal proliferation of CML progenitor cells, hence contributing to immune evasion." (PMID 40365344, 2025).
clear cell sarcoma (1 paper, 2021). A rare malignant neoplasm with melanocytic differentiation characterized by the presence of polygonal or spindle shaped clear cells. "Other less prevalent malignant kidney tumors included a renal cell carcinoma (RC), which showed a CD271+ CD81+ EpCAM+ CD71+ CD117+ phenotype in the absence of CD9, CD10, CD58, CD90, CD105, and GD2, and a clear cell sarcoma, which expressed CD271+ and GD2+ without EpCAM." (PMID 34638431, 2021).
Crohn disease (1 paper, 2010). A gastrointestinal disorder characterized by chronic inflammation involving all layers of the intestinal wall, noncaseating granulomas affecting the intestinal wall and regional lymph nodes, and transmural fibrosis. "Moreover, increased expression levels of ICAM-1 and LFA-3 (CD58) were also detected in monocytes from patients with Crohn's disease." (PMID 20072622, 2010).
demyelination (1 paper, 2023). "Furthermore, once the illness has begun, increased CD58 expression may guard against the onset of MS as well as moderate acute bouts of inflammatory demyelination." (PMID 37448727, 2023).
inflammatory skin disease (1 paper, 2022). Inflammatory skin disorders covers a broad category that includes many conditions ranging in severity, from mild itching to grave medical health complications These disorders are common in people of all ages and races. "Moreover, our findings may provide a molecular basis for selective interference with either CD6/CD166/CD318, or CD2/CD58, or both to specifically treat different types of inflammatory skin diseases." (PMID 36353616, 2022).
liver cancer (1 paper, 2024). An epithelial or non-epithelial malignant neoplasm that arises from the liver. "Both in vivo and in vitro assessments have conclusively demonstrated CD58’s functional role in enhancing the proliferation of liver cancer cells." (PMID 39156976, 2024). "Their research findings have established a correlation between increased CD58 expression and various clinicopathological features, including tumor size, differentiation level, and postoperative prognosis in liver cancer patients." (PMID 39156976, 2024).
lung adenocarcinoma (1 paper, 2025). A carcinoma that arises from the lung and is characterized by the presence of malignant glandular epithelial cells. "Conversely, CD58 expression was reduced in lung adenocarcinoma (LUAD) and lung squamous cell carcinoma (LUSC)." (PMID 41438981, 2025).
malignant kidney tumors (1 paper, 2021). "Tumor cells from all 17 malignant kidney neoplasms studied showed expression of CD271+ and CD81hi, together with positivity for EpCAM in the majority (12/17) of tumors (70%) and CD90 in 5/17 (29%), while they systematically lacked CD57, CD58, CD99, CD117, nuMyoD1, and numyogenin expression." (PMID 34638431, 2021).
myalgic encephalitis (1 paper, 2022). "Interestingly, altered CD58 expression was demonstrated in myalgic encephalitis, a disease characterizes by chronic fatigue." (PMID 36451826, 2022).
myocardial infarction (1 paper, 2019). Gross necrosis of the myocardium, as a result of interruption of the blood supply to the area, as in coronary thrombosis. "While some cells downregulated the respective pathways after incubation with myocardial infarction serum, the response of CD58/LFA-3 was completely abolished in up to 50% of cells." (PMID 30948775, 2019). "Serum of patients with myocardial infarction (MI) exerted the strongest effect on cells expressing CD58/LFA-3." (PMID 30948775, 2019).
Obesity (1 paper, 2025). Accumulation of substantial excess body fat. "Thus, CD11chigh pancreatic macrophages express molecules that promote T-cell adhesion and activation, including CD58 which is elevated in obesity." (PMID 40909804, 2025).
oligodendroglioma (1 paper, 2025). A well-differentiated (WHO grade II), diffusely infiltrating neuroglial tumor, typically located in the cerebral hemispheres. "Oligodendrogliomas lacking 1p19q co-deletion exhibit sensitivity to chemotherapy but are predisposed to recurrence, suggesting that CD58-targeted therapy could potentially delay disease recurrence." (PMID 41438981, 2025).
osteosarcoma (1 paper, 2023). A usually aggressive malignant bone-forming mesenchymal neoplasm, predominantly affecting adolescents and young adults. "Activation is particularly successful in osteosarcoma patients, as osteosarcoma cells have high expression of CD54 and CD58 cell-surface molecules, allowing for easy detection and stronger binding with NK cells." (PMID 37424864, 2023).
pancreatitis (1 paper, 2021). Inflammation of the pancreas. "The results suggested that CD58 was enhanced in pancreatitis and PDAC." (PMID 34193136, 2021). "In Oncomine, Logsdon’s data revealed that CD58 expression was notably enhanced in pancreatitis than the normal pancreas tissues (p = 0.030); Badea and Segara’s data manifested that CD58 level was markedly elevated in PDAC tissues than normal pancreas tissues (p < 0.001 for both)." (PMID 34193136, 2021). "CD58 expression was elevated in pancreatitis and PDAC tissues than normal pancreas or adjacent nontumor tissues." (PMID 34193136, 2021).
Pleural effusion (1 paper, 2021). The presence of an excessive amount of fluid in the pleural cavity. "At the advanced stage of HL, CD58 inactivation of HRS cells located in pleural effusions is extremely prevalent, which provides favorable conditions for the immune escape of tumor cells." (PMID 34168659, 2021).
T-cell leukemia (1 paper, 2008). A malignant disease of the T-lymphocytes in the bone marrow, thymus, and/or blood. "CD58-displaying BV bound to CD2-positive, but not CD2-negative Jurkat cells, a human T cell leukemia cell line." (PMID 19107192, 2008).
thymoma (1 paper, 2015). A neoplasm arising from the epithelial cells of the thymus. "Similar results were obtained on stimulation of transduced T cells with mouse thymoma BW5147 cells expressing a membrane-bound OKT3scFv and CD58 as costimulatory molecule (BW 3/2 CD58)." (PMID 25398767, 2015).
Wilms tumor (1 paper, 2013). An embryonal neoplasm characterized by the presence of epithelial, mesenchymal, and blastema components. "Conversely, the two Wilms tumors showed two clearly distinct (coexisting) tumor cell populations with a common CD56+ and CD58+, CD45−, CD99−, GD2−, nuMYOD1−, numyogenin−, CD10− and NG2− phenotype, but distinct reactivity (negative versus positive expression) for CD90, EpCAM and CD57." (PMID 23472067, 2013).
tumor (85 papers, 2002 to 2026). "Here, we revealed that AP-1-mediated activation was attenuated in CAR T cells impaired by tumor CD58 loss, driving a decrease in mitochondrial biogenesis, metabolic kinetic impairment, mitochondrial membrane potential loss and ROS accumulation." (PMID 41844571, 2026). "This approach was applied to patient-derived tumor–tumor-infiltrating lymphocyte cocultures, revealing that the loss of CD58 promotes IFN-γ-independent immune evasion." (PMID 40588529, 2025). "CD58 expression showed significant positive associations with CD8+ T cells in 9 tumor types, regulatory T cells (Tregs) in 19 tumors, neutrophils in 12 tumors, and B cells in 11 tumors." (PMID 41438981, 2025). "To evaluate CD58’s potential in predicting immunotherapy response, we analyzed its correlations with tumor mutational burden (TMB) and microsatellite instability (MSI) across multiple cancers." (PMID 41438981, 2025). "Conversely, high expression of CD58 in hepatocellular carcinoma and colorectal carcinoma has been linked to tumor development through the upregulation of the Wnt pathway." (PMID 40365344, 2025). "To study the regulatory mechanism of CD58 in the tumor microenvironment, we further analyzed the associations of CD58 with chemokines and PD-L1, immune-related genes, and found that the expression of CD58 was correlated with most chemokines." (PMID 41438981, 2025). "Loss of CD58 in tumor cells has been shown to compromise CAR-T cell activity, driving tumor-intrinsic resistance to T cell killing." (PMID 41295262, 2025). "Conversely, prior to CD19+CAR-T cell therapy, elevated CD58 expression in tumor samples was linked to improved clinical outcomes and survival rates." (PMID 40365344, 2025). "RP tumour-infiltrating myeloid cells expressed high levels of molecules associated with immunosuppression (CD58, CD80, CD163), as well as monocyte activation and dendritic cell maturation (CD40)." (PMID 37758326, 2024). "While CMTM6-deficient tumor cells exhibit PD-L1-dominant effects on T-cell activation, ectopic overexpression of CD58 reverses the affected T-cell activation and response to PD-L1 inhibition." (PMID 39349829, 2024). "High CD58 expression was substantially linked to large tumor size, poor differentiation, satellite focus, and vascular invasion (p < 0.05)." (PMID 37573318, 2023). "Accumulating evidence shows that CD58-expressing tumor cell is implicated in development of various cancers." (PMID 37573318, 2023). "To further examine this, we generated CMTM6-proficient and -deficient tumor cells that were either CD58 knockout or overexpressing CD58." (PMID 37683639, 2023). "Both Spearman’s rank correlation test and chi-squared test showed a significant association between CMTM6 and CD58 expression in tumor cells across the analyzed tumor samples." (PMID 37683639, 2023). "One group has recently reported that the loss of the adhesion/costimulatory molecule CD58 (the ligand of CD2) at the surface of tumor cells from large B-cell lymphoma patients is associated with CD19 CAR T-cell failure." (PMID 36189315, 2022). "Upregulated CD58 in cancer tissues was associated with worse histological grade, larger tumor size, and poorer overall survival and disease-free survival in PDAC patients." (PMID 34193136, 2021). "Recognition and elimination by T- and NK- cells are avoided by mutated CD58 and HLA-A genes, which both have increased incidence in rrDLBCLs compared to dDLBCLS suggesting decreased immunogenicity of the tumor cells in the refractory and relapsed situation." (PMID 34275438, 2021). "21% of DLBCLs, more frequently the ABC subtype, were found to have inactivation of the CD58 gene (CD58) that is implied in the loss of recognition of tumor cells by CTL and NK cells." (PMID 31934533, 2019). "This soluble form might compete with CD58 for binding, which could mess up antigen-presenting systems and be linked to tumor immune evasion and resistance to immunotherapy." (PMID 40365344, 2025).